IL32 (interleukin 32)
Diseases named in the same sentence as IL32 in open-access papers (continued):
Sharing a sentence is not in itself a finding about the gene and the disease.
autoimmune disease (16 papers, 2011 to 2025). A disorder resulting from loss of function or tissue destruction of an organ or multiple organs, arising from humoral or cellular immune responses of the individual to their own tissue constituents. "These genes included IL2RG and IL32, which are linked to autoimmune diseases, and IL7R, which is the most prominent example of a risk allele-associated alternatively spliced gene in MS." (PMID 40943121, 2025). "IL-32 has been found to be associated with various autoimmune diseases." (PMID 31616372, 2019). "IL-32, a secreted protein, has been reported to be associated with several autoimmune diseases." (PMID 27069296, 2016). "Understanding the contribution of MIAT in the regulation of Th17 response may offer new approaches to mitigate the inflammation in RA given its connection with IL-17 and its co-regulation with IL-32, another cytokine increasingly associated with autoimmune diseases, including RA." (PMID 35784351, 2022). "In addition, IL-32 is also associated with inflammatory diseases and autoimmune diseases." (PMID 29190960, 2017). "Clinical studies have investigated IL-32 under various conditions, such as viral infection, autoimmune diseases, inflammatory diseases, certain types of cancer, vascular disease, and pulmonary diseases." (PMID 35281066, 2022). "So far, the expression of IL-32 has been correlated with numerous autoimmune diseases, among them RA and IBD that were the most-studied conditions in this regard." (PMID 35281066, 2022). "IL-32, a proinflammatory cytokine, was shown to be upregulated at either mRNA or protein level in several autoimmune disorders; however, the precise role of this cytokine remains to be elucidated." (PMID 35142878, 2022). "In addition to autoimmune diseases, IL-32 is involved in respiratory inflammation conditions, such as COPD and asthma." (PMID 35281066, 2022). "In our setting, the increase of IL-32 levels, observed only in the patients with PAH, should be referred to the specific EC damage, associated with PAH, more than a disturbance of the immune-homeostasis, as reported for other autoimmune diseases." (PMID 32487240, 2020). "It has been reported that IL-32 may play a key role in the vascular alterations occurring during iPAH and showing a pro-inflammatory effect in several inflammatory and autoimmune diseases." (PMID 32487240, 2020). "All these findings further indicate that IL-32 might play a crucial role in the pathogenesis of autoimmune diseases." (PMID 31616372, 2019). "Recently, abnormal expression of interleukin-32 (IL-32) has been involved in various inflammatory or autoimmune diseases, but the level of IL-32 expression in Graves' disease (GD) is still unknown." (PMID 31616372, 2019). "As MM is closely related with autoimmune disease and chronic inflammation, high expression of IL-32 in MM cells may also contribute to the evolution of malignant plasma cells, which needs to be thoroughly explored." (PMID 29190960, 2017). "However, development of monoclonal antibodies to target extracellular IL-32 or adaption of siRNA approaches to knockdown intracellular IL-32 expression would allow this question to be addressed in both T1D and other autoimmune diseases where current evidence suggests a crucial role for IL-32." (PMID 40977709, 2025). "From these results, our data also suggest that the modulation of IL-32 through regulation of TLR3/TRIF and RIG-I pathways might be one of the major targets in inflammatory and/or autoimmune diseases, including ocular surface mucosa diseases." (PMID 25754842, 2015).
COVID-19 (14 papers, 2021 to 2026). A disease caused by infection with severe acute respiratory syndrome coronavirus 2. "Further research is needed to elucidate the underlying mechanisms regulating IL-32 expression in sepsis and COVID-19." (PMID 40149726, 2025). "IL-32 and IL-34 levels on admission were collected and tested for their association with CV disease and short-term mortality in patients with COVID-19." (PMID 36769623, 2023). "Thus, the primary aim of our study was to evaluate an association between IL-32/IL-34 with CV disease in the context of COVID-19." (PMID 36769623, 2023). "Depending on the underlying pathophysiological mechanisms of IL-32 and IL-34 release in COVID-19, one may suggest that these biomarkers can be of prognostic value if measured at a different time point." (PMID 36769623, 2023). "We suggested that high production of TNF, TNFRSF13B, and IL32 might be associated with and can serve as markers for COVID-19 severity." (PMID 35983322, 2022). "We suggest that high production of TNF, TNFRSF13B, and IL32 might be associated with and serve as markers for COVID-19 severity-specific therapies." (PMID 35983322, 2022). "COVID-19 patients exhibited a similar elevated IL-32 compared to unexposed controls (+0.29 ± 0.11 log10 pg/ml, p=0.016; 2.43 ± 0.08 hospital admission vs. pre-pandemic)." (PMID 41727490, 2026). "In the context of inflammatory diseases, mTreg upregulate IL-32 such as for patients with severe COVID-19." (PMID 39934117, 2025). "Conversely, a separate study observed decreased serum IL-32 levels in patients with mild, moderate, and severe COVID-19 compared to healthy individuals." (PMID 40149726, 2025). "While this represents the general hospitalized COVID-19 patient population well, it is possible that dynamics of IL-32 and IL-34 are different in pre-specified populations, such as patients requiring intensive care treatment upon admission." (PMID 36769623, 2023). "We also assessed the prognostic impact of IL-32/IL-34 and CV disease on short-term mortality in our well-defined study population of hospitalized patients with COVID-19." (PMID 36769623, 2023). "Several studies have investigated the role of IL-32 in COVID-19." (PMID 40149726, 2025). "Similarly, COVID-19 patients with mild, moderate, and severe disease exhibited a comparable reduction in IL-32 levels relative to healthy controls." (PMID 40149726, 2025). "Moreover, a small study of 64 patients with COVID-19 showed that concentrations of IL-32 were lower in patients with COVID-19 compared to healthy controls." (PMID 36769623, 2023). "Both interleukin-32 (IL-32) and interleukin-34 (IL-34) have been hypothesized to contribute to CV involvement in COVID-19." (PMID 36769623, 2023). "IL-32 and IL-34 were neither associated with CV disease nor with clinical endpoints in the context of COVID-19." (PMID 36769623, 2023). "Also, the interleukins (IL1B, IL15, IL16, and IL32) were found to be upregulated in the active COVID-19 patients, indicating a T cell and monocyte-mediated proinflammatory response during active COVID-19." (PMID 36532041, 2022). "IL-32 was elevated in all infected groups, suggesting that it can be the potential gene for producing the cytokines-induced inflammatory storm at each stage of the COVID-19 disease progression." (PMID 35983322, 2022). "IL-32 may contribute to quench both systemic and local inflammation, which may be effective in moderate COVID-19 patients, but likely fails in severe patients." (PMID 34422917, 2021). "However, there is not yet any solid evidence to clearly state the direct involvement among IL-32, 34 and 37 in the atherogenesis in COVID-19 patients." (PMID 34422917, 2021). "Interestingly, IL-32 levels were higher in the healthy controls than in patients with COVID-19." (PMID 40149726, 2025).
COVID-19 (continued). "However, despite the increased risk of atherosclerosis in COVID-19 patients—particularly in severe cases—no clear association has been observed between IL-32 levels and cardiovascular disease in these individuals." (PMID 40149726, 2025). "In addition, we speculate that the role of IL-32 and 37 may also be beneficial, but IL-34 may be harmful, during the course of COVID-19." (PMID 34422917, 2021). "We found that NKG7, IL32, GZMA, PRF1, CST7, GZMH, and CCL5 were among the top DEG downregulated in CD3+ upon nasal Foralumab treatment of COVID-19 subjects." (PMID 36881624, 2023). "One study reported elevated IL-32 levels in COVID-19 patients compared to healthy controls; however, IL-32 concentrations were not correlated with disease severity or survival." (PMID 40149726, 2025). "COVID-19 can induce cytokine storms, such as IL6, IL32, CD83, CCL2, CXCL11, the TNF family (TNFSF9 and the receptor TNFRSF9), and integrin-related genes, which exacerbates COVID-19 related myocarditis and decreases the prognosis of patients requiring ECMO treatment." (PMID 39026189, 2024). "Notably, COVID-19 patients with fever had significantly higher IL-32 levels than those without." (PMID 40149726, 2025).
Obesity (14 papers, 2017 to 2026). Accumulation of substantial excess body fat. "Obesity has been linked to increased IL-32 expression in visceral and subcutaneous adipose tissue as well as in peripheral blood mononuclear cells." (PMID 40149726, 2025). "There are inflammatory mediators associated with obesity and T2D, such as inteleukin-6 (IL-6), IL-32, tumor necrosis factor – α (TNF-α), that have a direct effect on vascular wall and plaque formation, but they are not within the scope of this work." (PMID 32337369, 2020). "IL-32 is known to be the pivotal regulator of liver inflammation caused by obesity." (PMID 37686029, 2023). "Furthermore, IL-32 levels have been reported to be associated with obesity-related inflammation and a correlation with disease severity in MASLD has been observed." (PMID 37686029, 2023). "Increased IL-32 expression has been found in visceral adipose tissue from patients with obesity promoting inflammation and extracellular matrix remodeling and contributing to the development of obesity-associated comorbidities." (PMID 31694146, 2019). "have reported the high expression of IL32 in skeletal muscles in the context of obesity‐related sarcopenia." (PMID 41457346, 2026). "According to DNA microarray analysis and transcriptomics of tissue samples from patients with MASLD and obesity, IL-32 is a deregulated gene that is correlated with NAS, insulin resistance and aminotransferase levels." (PMID 39939782, 2025). "In addition, according to a previous report, IL32 is suspected to be involved in obesity‐related sarcopenia." (PMID 41457346, 2026). "However, pro- or antitumor activity which is dependant on obesity, gender, and age as it relates to IL-32 has yet to be studied." (PMID 35281008, 2022). "Obesity-related IL-32 regulation indicated the role of IL-32 in cancer metabolism and inflammation." (PMID 35281008, 2022). "Our study identifies IL-32 as a novel myogenic regulator, provides a comprehensive map of the dynamic epigenome during differentiation of human muscle stem cells and reveals abnormal epigenetic changes in obesity." (PMID 28222718, 2017). "However, obesity-related IL-32 manipulation indicates that IL-32 could play a role in cancer metabolism as well as inflammation." (PMID 35281008, 2022). "In agreement with this study, we observed a positive correlation between hepatic IL-32 expression and steatosis as well as fibrosis grade in the MASLD patients, albeit only a weak correlation with inflammation and obesity." (PMID 37686029, 2023). "Among the rNK cells, cluster C0 expressed mediators known to participate in inflammation during obesity (CCL5 and IL32)." (PMID 37063898, 2023). "Specifically, we observed the levels of IL-1β, IL-6, IL-8, IL-12, IL-17, IL-21, IL-32, and TNF-α were significantly higher in the NAFLD group than in the simple obesity group (all P < 0.001)." (PMID 36530698, 2022). "We found that plasma IL-1β, IL-6, IL-8, IL-12, IL-17, IL-21, IL-32, and TNF-α levels were elevated in obese children with NAFLD compared to subjects with simple obesity." (PMID 36530698, 2022). "In the group of obese children without NAFLD (i.e., the simple obesity group), we found that inflammatory markers IL-6 and IL-32 exhibited the highest number of significant correlations." (PMID 36530698, 2022). "In addition, IL32 has been shown to have inflammatory properties in human obesity and have a negative impact on insulin sensitivity and myogenesis, while TNFRSF12/FN14 has been implicated in various muscle wasting diseases and metabolic dysfunction." (PMID 32624006, 2020).
pancreatic cancer (14 papers, 2001 to 2024). "Most GI cancers include esophageal, gastric, liver (e.g., HCC), and pancreatic cancers, were found to express higher levels of IL-32, and mostly exhibit a facilitating cancer progression role." (PMID 35281008, 2022). "The PI3-kinase pathway has been shown to induce IL-32 expression in a number of studies, especially in pancreatic cancer where its pro- cancerous role has been established." (PMID 23189187, 2012). "The mechanisms regulating IL-32 expression have been examined in several reports using vascular endothelial cells, synovial fibroblasts, and pancreatic cancer cell lines." (PMID 22413812, 2012). "Moreover, similar activity for IL-32 in promoting cancer growth and survival was reported in pancreatic cancer." (PMID 35281008, 2022). "However, other studies have suggested that IL-32 decreases tumor development, including cervical cancer, colon cancer, prostate cancer, melanoma, pancreatic cancer, liver cancer, and chronic myeloid leukemia." (PMID 35069212, 2021). "We hypothesized that since cancer tissues have an increased expression of IL-32, this indicated the potential involvement of this cytokine in cancer growth, for example in pancreatic cancer." (PMID 25435980, 2015).
Arthritis (12 papers, 2006 to 2026). Inflammation of a joint. "Animal model studies have shown that an intra-articular injection of IL-32 induces arthritis and joint damage, with a correlation between synovial inflammation severity and IL-32 levels, indicating a potential pathogenic role of IL-32 in RA." (PMID 40299461, 2025). "Preclinical studies have demonstrated that genetic or pharmacologic inhibition of IL-32 attenuates experimental arthritis severity, underscoring its therapeutic potential." (PMID 41685297, 2026). "Some of the newer cytokines such as IL-32, IL-34 and IL-35 are being investigated for their role in the pathogenesis and treatment of arthritis." (PMID 25561237, 2014). "We examined the in vivo relationship between IL-32 and TNFα, and the pathologic role of IL-32 in the TNFα-related diseases – arthritis and colitis." (PMID 17078892, 2006). "The fact that the IL-32-related cytokines, TNFα and IL-18, show a close correlation with arthritis implies that IL-32 has a pathologic role in inflammatory diseases." (PMID 17078892, 2006). "Although functional differences between these isoforms remain unknown, the significant role of IL-32 has been reported in the development of several diseases, including arthritis, psoriasis, ulcerative colitis and Crohn's disease." (PMID 25754842, 2015). "In addition, IL-32 expression was correlated with IL-18 expression in the synovia of experimental arthritis animals and mucosa of patients with allergic rhinitis." (PMID 26634249, 2015). "Furthermore, the relatively newer cytokines such as IL-32, IL-34 and IL-35 are being investigated for their potential role in the pathogenesis and treatment of arthritis." (PMID 25561237, 2014). "It was clear that T cells proliferated in the synovial tissue of PsA mice and enhanced arthritis by producing CXCL14 and IL-32, which likely exacerbated local and systemic inflammation." (PMID 39114979, 2024). "Moreover, the question of whether IL-32 plays a pathological role in animal models other than arthritis has not been addressed." (PMID 17078892, 2006).
atopic dermatitis (12 papers, 2012 to 2025). "In atopic dermatitis, IL-32 plays a key role in the interaction between keratinocytes and Langerhans cells and contributes to the inflammatory process, providing a potential therapeutic target." (PMID 37727785, 2023). "IL-32 levels in skin lesions of atopic dermatitis, hidradenitis suppurativa and alopecia areata are increased compared to healthy skin." (PMID 37727785, 2023). "The following review summarizes the different roles of the various IL-32 isoforms in the context of skin inflammation, with a focus on atopic dermatitis." (PMID 37727785, 2023). "This study aims to explore the mechanism of interleukin-32 (IL-32) affecting atopic dermatitis (AD) through the Janus-activated kinase-1 (JAK1)/microRNA-155 (miR-155) axis." (PMID 35545774, 2022). "In IBD IL-32α was elevated in the mucosa (reviewed), whilst in atopic dermatitis, serum levels of IL-32 correlated to severity and were reduced with successful treatment, potentially implicating IL-32 as a useful biomarker for disease progression and favorable therapy responses." (PMID 40977709, 2025). "IL-32 expression was also detected in KCs in atopic dermatitis." (PMID 33941102, 2021). "Furthermore, higher expression of IL-32 has been reported in human epidermal keratinocytes of atopic dermatitis, correlating with the severity of the diseases." (PMID 32487240, 2020). "Importantly, an elevated IL-32 level was found in the sera of patients with atopic dermatitis, asthmatic patients, systemic lupus erythematosus, etc., indicating that IL-32 was produced by blood cells." (PMID 29538330, 2018). "We hypothesized that overexpression of IL32 in hair follicle keratinocytes of patients with atopic dermatitis would lead to the excessive production of pro-IL1β and that the activation of IL1β from pro-IL1β by inflammasome complex, in which NLRP2 protein might be involved, would be augmented." (PMID 23385231, 2013). "Serum IL-32 has been shown to be elevated in several diseases, including type 2 diabetes, cancer, systemic lupus erythematosus, HIV infection, and atopic diseases including atopic dermatitis." (PMID 37727785, 2023). "Interestingly, IL-32 is expressed by human primary keratinocytes and modulates keratinocyte apoptosis in atopic dermatitis, whereas it was not present in either skin biopsy specimens from healthy donors or lesioned skin from patients with psoriasis." (PMID 27528123, 2016).